TRAF6 (TNF receptor associated factor 6)
Description:
E3 ubiquitin ligase that, together with UBE2N and UBE2V1, mediates the synthesis of 'Lys-63'-linked-polyubiquitin chains conjugated to proteins, such as ECSIT, IKBKG, IRAK1, AKT1 and AKT2. Also mediates ubiquitination of free/unanchored polyubiquitin chain that leads to MAP3K7 activation. Leads to the activation of NF-kappa-B and JUN. Seems to also play a role in dendritic cells (DCs) maturation and/or activation (By similarity). Represses c-Myb-mediated transactivation, in B-lymphocytes. Adapter protein that seems to play a role in signal transduction initiated via TNF receptor, IL-1 receptor and IL-17 receptor. Regulates osteoclast differentiation by mediating the activation of adapter protein complex 1 (AP-1) and NF-kappa-B, in response to RANK-L stimulation (By similarity). Together with MAP3K8, mediates CD40 signals that activate ERK in B-cells and macrophages, and thus may play a role in the regulation of immunoglobulin production (By similarity). Acts as a regulator of the JNK and NF-kappa-B signaling pathways by initiating assembly of heterotypic 'Lys-63'-/'Lys-48'-linked branched ubiquitin chains that are then recognized by TAB2: TRAF6 catalyzes initial 'Lys-63'-linked-polyubiquitin chains that are then branched via 'Lys-48'-linked polyubiquitin by HUWE1. 'Lys-63'-/'Lys-48'-linked branched ubiquitin chains protect 'Lys-63'-linkages from CYLD deubiquitination. Participates also in the TCR signaling by ubiquitinating LAT.
Synonyms: RNF85; MGC:3310
Tractability: Antibody: its Gene Ontology location is reachable by antibodies, with high confidence. PROTAC: UniProt records ubiquitination sites on it; ubiquitination databases record sites on it; its protein half-life has been measured.
Target class: Enzyme; Ligase
Gene: Protein-coding gene on chromosome 11 (36,483,769 to 36,510,292, reverse strand). Ensembl gene ENSG00000175104.
Subcellular location: Cytoplasm; Cytoplasm, cell cortex; Nucleus; Lipid droplet
Subcellular location (Human Protein Atlas): Mitochondria; Nucleoli
Pathways (Reactome):
Immune System: Alpha-protein kinase 1 signaling pathway; CLEC7A (Dectin-1) signaling; Downstream TCR signaling; FCERI mediated NF-kB activation; IKK complex recruitment mediated by RIP1; IRAK1 recruits IKK complex; IRAK1 recruits IKK complex upon TLR7/8 or 9 stimulation; IRAK2 mediated activation of TAK1 complex; IRAK2 mediated activation of TAK1 complex upon TLR7/8 or 9 stimulation; Interleukin-1 signaling; JNK (c-Jun kinases) phosphorylation and activation mediated by activated human TAK1; MyD88 cascade initiated on plasma membrane; MyD88 dependent cascade initiated on endosome; MyD88:MAL(TIRAP) cascade initiated on plasma membrane; NOD1/2 Signaling Pathway; Regulation of NF-kappa B signaling; TAK1-dependent IKK and NF-kappa-B activation; TICAM1, RIP1-mediated IKK complex recruitment; TICAM1,TRAF6-dependent induction of TAK1 complex; TRAF6 mediated IRF7 activation; TRAF6 mediated IRF7 activation in TLR7/8 or 9 signaling; TRAF6 mediated NF-kB activation; TRAF6 mediated induction of NFkB and MAP kinases upon TLR7/8 or 9 activation; TRAF6-mediated induction of TAK1 complex within TLR4 complex; activated TAK1 mediates p38 MAPK activation
Signal Transduction: NF-kB is activated and signals survival; NRIF signals cell death from the nucleus; PI5P, PP2A and IER3 Regulate PI3K/AKT Signaling; PIP3 activates AKT signaling; Regulated proteolysis of p75NTR; p75NTR recruits signalling complexes
Disease: SARS-CoV-1 activates/modulates innate immune responses; SARS-CoV-2 activates/modulates innate and adaptive immune responses
Metabolism of proteins: Ovarian tumor domain proteases; Ub-specific processing proteases
Gene Ontology:
Molecular function: histone deacetylase binding; identical protein binding; protein binding; protein kinase B binding; protein-macromolecule adaptor activity; ubiquitin conjugating enzyme binding; ubiquitin protein ligase activity; ubiquitin-protein transferase activity; ubiquitin-ubiquitin ligase activity; signaling adaptor activity; enzyme binding; tumor necrosis factor receptor binding; zinc ion binding
Biological process: antiviral innate immune response; autophagosome assembly; canonical NF-kappaB signal transduction; CD40 signaling pathway; cellular response to cytokine stimulus; cellular response to lipopolysaccharide; cytoplasmic pattern recognition receptor signaling pathway; interleukin-17A-mediated signaling pathway; interleukin-33-mediated signaling pathway; negative regulation of DNA-templated transcription; negative regulation of transcription by RNA polymerase II; non-canonical NF-kappaB signal transduction; positive regulation of canonical NF-kappaB signal transduction; positive regulation of interleukin-2 production; positive regulation of JNK cascade; positive regulation of leukocyte adhesion to vascular endothelial cell; positive regulation of osteoclast differentiation; positive regulation of T cell cytokine production; positive regulation of transcription by RNA polymerase II; protein autoubiquitination; protein branched polyubiquitination; protein K63-linked ubiquitination; protein polyubiquitination; response to interleukin-1; T cell receptor signaling pathway; and 27 more
Cellular component: cytoplasm; nucleus; perinuclear region of cytoplasm; plasma membrane; protein-containing complex; ubiquitin ligase complex; CD40 receptor complex; cytoplasmic side of plasma membrane; cytosol; endosome membrane; extrinsic component of cytoplasmic side of plasma membrane; glutamatergic synapse; lipid droplet; cell cortex
Genetic constraint (gnomAD): Loss-of-function variants: 9 observed, 44.14 expected, observed/expected ratio (o/e) 0.2, 90% interval 0.12 to 0.36. The upper end of that interval is the gene's LOEUF score, 0.36, which puts it in group 1 of 6, group 1 being the genes least tolerant of losing a copy. Missense variants: 376 observed, 659.04 expected, observed/expected ratio (o/e) 0.57, 90% interval 0.52 to 0.62. Synonymous variants: 177 observed, 218.91 expected, observed/expected ratio (o/e) 0.81, 90% interval 0.71 to 0.92.
Homologues: Orthologues: chimpanzee TRAF6 (99% identical), macaque TRAF6 (98% identical), pig TRAF6 (93% identical), guinea pig TRAF6 (93% identical), rabbit TRAF6 (93% identical), mouse Traf6 (89% identical), rat Traf6 (88% identical), dog TRAF6 (86% identical), tropical clawed frog traf6 (69% identical), zebrafish traf6 (57% identical), Drosophila melanogaster Traf6 (25% identical). Paralogues in human: TRAF2 (26% identical), TRAF5 (26% identical), TRAF3 (25% identical), TRAF4 (23% identical), TRAF1 (17% identical).
Diseases named in the same sentence as TRAF6 in open-access papers:
TRAF6 is named in the same sentence as 329 diseases in open-access papers, as found by Europe PMC text mining. Sharing a sentence is not in itself a finding about the gene and the disease. The quoted sentences say what the papers report.
lung carcinoma (52 papers, 2013 to 2026). "Autophagy induced by TLR4 or TLR3 activation stimulates multiple cytokine productions via TRAF6 K63-linked ubiquitination and thus facilitates progression of lung cancer cells." (PMID 36202787, 2022). "TRAF6 upregulation and K63-linked ubiquitination is found in lung cancer cells, while TRAF6 knockdown suppresses the invasion of lung cancer cells." (PMID 36202787, 2022). "TNF receptor‐associated factor 6 (TRAF6) promotes the development of human lung cancer through bridging RAS and NF‐kB pathways; on the other hand, thioredoxin‐interacting protein (TXNIP) suppresses the growth of tumors." (PMID 31578830, 2020). "It has been proven that tumor necrosis factor receptor-associated factor 6 (TRAF6) was a commonly amplified oncogene in lung cancer." (PMID 26582220, 2015). "In addition to autoimmune diseases, accumulating evidence indicates that TRAF6 is associated with the progression of various types of tumors, including breast cancer, hepatocellular carcinoma, and lung cancer." (PMID 33294443, 2020). "Our study provides evidence that polymorphism in miR-146a rs2910164 C>G might alter individual susceptibility to lung cancer through inhibiting miR-146a expression and secondary structure, as well as directly influencing the target gene TRAF6." (PMID 27911870, 2017). "This study is the first to provide evidence that common SNP rs2910164 in miR-146a might be an important factor in lung cancer risk through disrupting miR-146a expression and secondary structure as well as directly inhibiting the target gene TRAF6." (PMID 27911870, 2017). "TRAF6 overexpression is associated with lung cancer tumourigenesis and invasion." (PMID 28751780, 2017). "In this research, we focused on the positive compound EGCG, which is a new inhibitor of E3 ligase targeting the N-terminal RING domain to potentially prevent and treat melanoma, lung cancer, and other tumors by targeting TRAF6." (PMID 38921571, 2024). "A comprehensive analysis of chromosome amplification in lung cancer has identified TRAF6 as a critical oncogene in RAS-mediated tumorigenesis." (PMID 38169510, 2024). "This is substantiated by increased levels of TRAF6 observed in several lung cancer cell lines, including A549, HCC827, NCI-H292, and 95-D, as well as human bronchial epithelial cells." (PMID 38169510, 2024). "TRAF6 is of vital importance in pregnancy‐induced epithelial cell proliferation, and its downregulation reduces invasion and metastasis in melanoma and lung cancer." (PMID 38164738, 2024). "TRAF6 is an important gene in the NF-κB signal pathway and has a critical role in lung cancer tumorigenesis." (PMID 36800962, 2023). "Recently, it has been reported that autophagy can facilitate TLR4- and TLR3-triggered migration and invasion of lung cancer cells through the promotion of TRAF6 ubiquitination." (PMID 37443143, 2023). "MiR-146a regulates the main gene TRAF6 and continually Bcl2 via the NF-KB signaling pathway that induces apoptosis in lung cancer." (PMID 36800962, 2023). "Multiple studies have demonstrated that TRAF6 exhibits abnormal overexpression in various malignant tumors, including lung cancer, colon cancer, and melanoma, and plays a crucial role in regulating tumor cell proliferation, migration, and invasion." (PMID 38062041, 2023). "For example, in human lung cancer cells, TRAF6 interacts with and ubiquitinates PI3K, leading to phosphorylation of AKT at T308 and S473, which endows cancer cells with resistance to apoptosis." (PMID 37484971, 2023). "It has been further reported that CLU inhibits lung cancer progression by inhibiting TGFBR1-induced TRAF6/TAB2/TAK1 complex recruitment and thus blocking the TAK1-NF-κB axis, indicating its tumor-suppressive function, which is consistent with our in vivo data." (PMID 35626071, 2022). "The knockdown of TRAF6 expression promotes apoptosis and inhibits the invasion of human lung cancer cells and osteosarcoma." (PMID 36010884, 2022).
lung carcinoma (continued). "The role of TRAF6 as an oncogene in cancer has recently emerged, as TRAF6 is amplified in several types of cancer, such as lung carcinoma, advanced prostate cancer, gastric carcinoma and bladder cancer, and promotes angiogenesis and glioblastoma progression." (PMID 35625561, 2022). "TNF receptor-associated factor 6 (TRAF6)-BECN1 signaling axis plays a pivotal role in autophagy induction through ubiquitination of BECN1, thereby inducing lung cancer migration and invasion in response to toll-like receptor 4 (TLR4) stimulation." (PMID 35422093, 2022). "Previous reports have demonstrated that TLR3/4 activation can increase the production of IL-6, CCL2, MMP2, and CCL20 cytokines by promoting TRAF6 ubiquitination and autophagy induction, thereby facilitating the migration and invasion of lung cancer cells." (PMID 35422093, 2022). "Autophagy induced by TLR4 or TLR3 activation can enhance the production of cytokines such as IL-6, CCL2, MMP2, and CCL20 by promoting TRAF6 ubiquitination, thus facilitating the migration and invasion of lung cancer cells." (PMID 35422093, 2022). "In lung cancer, TRAF6 was found to be overexpressed and the overexpression was closely associated with the clinical TNM stage, tumor size, and lymph node metastasis." (PMID 34409101, 2021). "Compared with that of healthy control, the expression of TRAF6 was markedly augmented in MDSCs from PBMCs of lung cancer patients." (PMID 33717204, 2021). "In lung cancer, TRAF6 locus amplification was found to occur frequently, and TRAF6 plays an important role in connecting RAS and NF-κB signaling pathways." (PMID 34409101, 2021). "Inhibition of TRAF6 in human lung cancer cells suppressed NF-κB activation, anchorage-independent and tumour growth." (PMID 34503110, 2021). "Over-expression of TRAF6 gene aligned with the amplification of chromosome 11 at band p13 was proposed to constitute the MAPK pathway activation in human lung cancer development." (PMID 33015045, 2020). "It was previously shown that downregulation of TRAF6 decreases cell viability, suppresses cell proliferation, and promotes cell apoptosis in lung cancer cells." (PMID 28751780, 2017). "Meanwhile, the inhibition of TRAF6 expression can significantly inhibit the proliferation and invasion of pancreatic cancer, breast cancer, lung cancer, esophageal cancer, multiple myeloma, and other cells." (PMID 28592924, 2017). "A recent study has shown that autophagy facilitates toll-like receptor (TLR) 4 (TLR4)- and TLR3-triggered migration and invasion of lung cancer cells through promoting TRAF6 ubiquitination." (PMID 29326710, 2017). "In recent years TRAF6 has been found to play some roles in carcinogenesis in some cancers, such as lung cancer, glioblastoma, and squamous cell carcinoma." (PMID 27708550, 2016). "TRAF6 is among the oncogenes that are amplified in lung cancer, and the knockdown of TRAF6 expression significantly attenuates cell growth, tumor formation and Ras-mediated tumor formation." (PMID 27791197, 2016). "This study analyzed the effects of TRAF6 on the proliferation, apoptosis, cell cycle, migration, and invasion capability of lung cancer cell lines, as well as the potential molecular mechanisms involved." (PMID 26582220, 2015). "Inhibition of TRAF6 in human lung cancer cells suppressed NF-κB activation, anchorage-independent growth and tumor formation." (PMID 24902858, 2014). "Downregulation of TRAF6 in human lung cancer and osteosarcoma cells suppresses NF-κB activation, cell survival and proliferation, and tumor formation and invasion." (PMID 23758787, 2013). "In conclusion, the current results showed that Rosa synergistically improves the chemotherapeutic potential of cisplatin in lung cancer cells by suppressing the TLR2/MyD88/ TRAF6/NF-κB signal pathway together with the PI3K/AKT/mTOR and Gal-1 which consequently, inhibits proliferation." (PMID 40022036, 2025).
lung carcinoma (continued). "Furthermore, autophagy, stimulated by either TLR4 or TLR3 activation, promotes the generation of various cytokines by elevating TRAF6 ubiquitination, which consequently fosters lung cancer cell invasion and migration." (PMID 38169510, 2024). "Extensive research has provided evidence of the potential oncogenic role of TRAF6 in lung cancer." (PMID 38169510, 2024). "Furthermore, extensive research has focused on the involvement of TRAF6 in autophagy induction during lung cancer development." (PMID 38169510, 2024). "Based on these results, we determined whether ARRB2 could negatively regulate autophagy induced by TLR signals through the regulation of TRAF6 ubiquitination, thereby inhibiting the migration and invasion of lung cancer." (PMID 37443143, 2023). "TRAF6 is a direct target of miR-146a-5p in lung cancer cells." (PMID 36800962, 2023). "In addition, a previous report has shown that autophagy can facilitate TLR4- and TLR3-triggered migration and invasion of lung cancer cells by promoting TRAF6 ubiquitination." (PMID 37443143, 2023). "In addition, the expression of TRAF6 was increased in MDSCs from lung cancer patients, which was positively correlated with the level of Arg1 in MDSCs." (PMID 33717204, 2021). "Taken together, our studies revealed the mechanism by which TRAF6 exerts its role in NSCLC development and suggested TRAF6 maybe was a promising candidate target for lung cancer prevention and therapy." (PMID 34409101, 2021). "Considering that TRAF6 improves the function of MDSCs in mice, we examined whether TRAF6 had similar characteristics in MDSCs from lung cancer patients." (PMID 33717204, 2021). "Thus, TRAF6 acted as an oncogene leading to the constitutive NF-κB activation in K-Ras-driven lung cancers." (PMID 34503110, 2021). "TRAF6 and arginase 1 were highly expressed in MDSCs of patients with lung cancer." (PMID 33717204, 2021). "Similarly, the inhibition of TRAF6 can inhibit the migration and invasion of human lung cancer SPC-A1 cells, MCF-7 breast cancer cell lines, SCCHN cells, and GBM cells and promote their apoptosis." (PMID 33294443, 2020). "Indeed, TRAF6 is a putative oncogene in a variety of cancers including lung cancer, bladder cancer, breast cancer, prostate cancer and skin cancer." (PMID 30643010, 2019). "Furthermore, a recent report has shown that autophagy functions to TLR4- and TLR3-triggered progression of lung cancer cells through enhancing TRAF6 ubiquitination, indicating the pivotal role of autophagy in cancer progression." (PMID 31620128, 2019). "TRAF6 downregulation of decreases levels of p-p65 in the lung cancer cell line A549." (PMID 28751780, 2017). "Our previous study got the conclusion that TRAF6 may become a target for diagnosis and gene treatment for lung cancer patients as the TRAF6 had a higher level of expression in lung cancer tissues than in normal lung tissues." (PMID 27708550, 2016). "TRAF6 was shown to be an important oncogene for RAS-mediated oncogenesis in lung cancers." (PMID 25242495, 2014). "Interestingly, TRAF6 has been shown to be amplified in lung cancers and to function as an oncogene required for Ras-induced transformation." (PMID 24955217, 2014). "TRAF6 exhibits overexpression and gene amplification in lung cancer and osteosarcoma cells." (PMID 23758787, 2013). "The binding of TLR2 to the adapter protein MyD88 recruits TRAF6 which consequently promotes the activation of the NF-κB Thus, the activation of this pathway may enhance carcinogenesis and development of lung cancer in addition to regulating cancer proliferation." (PMID 40022036, 2025). "Importantly, recent studies have reported that autophagy facilitates TLR-induced migration and invasion of lung cancer cells through the TRAF6-induced ubiquitination of BECN1, suggesting that TLR-induced autophagy is functionally associated with lung cancer progression." (PMID 35422093, 2022).